ATP2B4 (ATPase plasma membrane Ca2+ transporting 4)
Diseases named in the same sentence as ATP2B4 in open-access papers (continued):
Sharing a sentence is not in itself a finding about the gene and the disease.
malaria (continued). "Two target genes were chosen, Basigin (BSG, CD147) which is known to be a universal receptor for P. falciparum invasion as a proof of principle, and ATP2B4 (PMCA4) since natural variation in this gene has been correlated to resistance to severe malaria." (PMID 38173794, 2023). "GWAS has identified numerous SNPs associated with severe Plasmodium infections, however, only a few variant genes and their polymorphisms, such as ATP2B4 and HBB, have been experimentally confirmed to be involved with malaria pathogenesis." (PMID 35646724, 2022). "This study confirmed results in two earlier GWAS (one in Ghana and one multi-site across Africa, Asia and Oceania) identifying ATP2B4 as a significant resistance loci for severe malaria." (PMID 34215257, 2021). "The GWASs have replicated some of the well-known malaria resistance genomic risk loci including sickle cell (HBB) and ABO blood group loci and identified new variants in ATP2B4 and Glycophorin regions." (PMID 34868193, 2021). "Genome-wide association studies have identified 4 genetic determinants of severe malaria risk in this population (ABO blood group, HbS, Dantu blood group, and ATP2B4)." (PMID 32536341, 2020). "We first discuss the biology of two variants such as cluster of the glycophorin genes (GYPA/B/E) and ATP2B4 that were well-replicated across malaria endemic populations." (PMID 31409341, 2019). "We identified in Northern Ugandans a strong signal of malaria-driven selection in the ATP2B4 gene coding for a calcium transporter expressed in erythrocytes." (PMID 30849090, 2019). "By comparing the populations with the highest malaria pressures versus those with no malaria, we identified for the first time a candidate region for malaria-driven selection in the ATP2B4 gene in African, specifically Northern Ugandan populations." (PMID 30849090, 2019). "We found that all Bubi individuals possessed the malaria-resistant allele of the ACKR1 and CD36 genes, in addition to certain variations in other genes such as G6PD, ATP2B4, GRK5, and IL-10." (PMID 30841922, 2019). "We have described the effects of both ATP2B4 and Dantu on specific phenotypes of severe malaria, on parasite densities during malaria episodes, on haematological indices, and on death during hospital admission." (PMID 30033078, 2018). "Genetic variation within an erythroid-specific DNase I hypersensitive site in an intron of ATP2B4 has been identified as a key molecular basis affecting plasma membrane calcium ATPase isoform 4b (PMCA4b) expression and conferring innate resistance to malaria." (PMID 40993672, 2025). "There was, nevertheless, no report of association analysis of ATP2B4 single nucleotide polymorphisms (SNP) with parasitaemia or mild malaria." (PMID 36849945, 2023). "The data support the hypothesis that this ATP2B4 genotype, common in The Gambia and other malaria-endemic areas, protects against severe malaria through the suppression of parasitaemia during an infection." (PMID 36604655, 2023). "Functional annotation of the malaria-protective ATP2B4 SNPs in the recent GWAS carried out by the Malaria Genomic Epidemiology Network also found that these SNPs regulate ATP2B4 gene expression by disrupting the promoter upstream of the gene’s transcription start site." (PMID 32130487, 2020). "However, the protective effect at ATP2B4 appears substantially stronger than this trend and suggests a genuinely pleiotropic effect whose mechanism against malaria is yet to be determined." (PMID 31844061, 2019). "Importantly, we identified for the first time in Africa a Northern Uganda-specific strong signal of malaria-driven selection in the ATP2B4 gene." (PMID 30849090, 2019). "Characterization of biological relationships between the ATP2B4 gene and malaria may inform the investigation of complex genomic disease associations in eBL belt populations." (PMID 30849090, 2019).
malaria (continued). "The strong performance of our method in the context of a very well established predictor of malaria resistance, Hemoglobin S, serves as a positive control (method validation), and this further suggests that the conclusions about ATP2B4 and MARVELD3 should be useful." (PMID 25071867, 2014). "The investigation also confirmed other loci previously associated with erythrocyte function and important for protection against malaria such as HBB, ABO, and ATP2B4, and that many of these alleles may have been under balancing selection that predated the human non-human primate split." (PMID 35646724, 2022). "We could not confirm that polymorphisms in the ATP2B4 locus (rs10900585, rs4951074, rs55868763, rs3753036, and rs1541255) were associated with severe malaria (P > .25)." (PMID 25805752, 2015). "Among these genes, some were previously shown to play a role in severe malaria, specially CXCL10, ARG1, ATP2B4, and MMP9." (PMID 32801995, 2020). "While polymorphisms in the ATP2B4 gene were described as protective against severe malaria in Ghana and Gambia, the outlier approach used in the present study did not identify ATP2B4 as a candidate selection gene in Ghanaians and Nigerians." (PMID 30849090, 2019). "Although previous studies have highlighted associations between polymorphisms in ATP2B4 and FREM3 and malaria risk, they have lacked detail about the precise clinical effects of these polymorphisms." (PMID 30033078, 2018). "Nevertheless, by contrast with sickle-cell trait, ATP2B4, and blood group O, we saw no discernible effect of rs186873296 on parasite densities in severe malaria cases within our study." (PMID 30033078, 2018).
melanoma (16 papers, 2017 to 2025). A malignant, usually aggressive tumor composed of atypical, neoplastic melanocytes. "ATP2B4, as a gene participating the transportation of Ca2+, has been confirmed that its overexpression could inhibit the progress and migration of melanoma cells with BRAF mutation." (PMID 35097120, 2022). "More recently, plasma membrane Ca2+ pump isoform 4b (PMCA4b or ATP2B4) has been established as a metastasis suppressor in BRAF mutant melanoma cells." (PMID 35409206, 2022). "Previously, we identified the plasma membrane Ca2+ pump isoform 4b (PMCA4b or ATP2B4) as a putative metastasis suppressor in BRAF mutant melanoma cells." (PMID 32414111, 2020). "By analyzing the relative abundance of the transcripts and proteins across all the samples both in the TCGA and MM500 databases, ATP2B4 was close to the best-fitting curve suggesting a strong correlation between transcript and protein abundance in melanoma tissues." (PMID 35328746, 2022). "Three ATP2B4–RASGRF2 fusions and two ERBIN–RASGRF2 fusions have been previously reported in melanocytic proliferations (n = 4) and a single melanoma lacking other RAS-activating oncogenic alterations." (PMID 40615519, 2025).
breast carcinoma (12 papers, 2016 to 2025). "Here we demonstrate that the plasma membrane Ca2+ pump PMCA4 (ATP2B4) is downregulated in luminal breast cancer, and this is associated with shorter relapse-free survival in patients with luminal A and B1 subtype tumors." (PMID 40075218, 2025). "In the present study we show that PMCA4(b) (assessed by a PMCA4-specific antibody) is downregulated in luminal-type breast carcinoma tissue samples, and that the expression level of the ATP2B4 gene correlates with patient survival." (PMID 40075218, 2025). "Publicly available data revealed significantly lower ATP2B4 mRNA expression in breast carcinomas when compared to normal breast tissue." (PMID 30352569, 2018). "To further study the role of ER-α in the regulation of PMCA4 expression, we analyzed data from chromatin immunoprecipitation sequencing (ChIP-seq) experiments of ER-α binding to the ATP2B4 gene locus in ER-α positive breast cancer cells." (PMID 30352569, 2018). "Previous in vitro studies showed upregulated ATP2B1 and ATP2B2 mRNA and downregulated ATP2B4 mRNA expression in some breast cancer cell lines." (PMID 30352569, 2018). "Three distinct datasets displayed significantly lower ATP2B4 mRNA expression in invasive breast cancer tissue samples compared to normal breast tissue, whereas the expression of ATP2B1 and ATP2B2 was not altered." (PMID 30352569, 2018). "While PMCA2 (ATP2B2) was upregulated in HER+ breast cancer tumors, PMCA4 (ATP2B4) was downregulated in colon and prostate cancers, and lymph node metastases in contrast to the relatively high PMCA4 protein level in normal tissues." (PMID 33802790, 2021). "In breast cancer cells upregulated ATP2B1, ATP2B2 mRNA and downregulated ATP2B4 mRNA expressions were described previously." (PMID 30352569, 2018). "Consistent with the IHC data presented above, there were individual breast cancers with relative high levels of PMCA2 (ATP2B2) in all of the molecular subtypes, this was not seen for PMCA1 (ATP2B1) or PMCA4 (ATP2B4)." (PMID 27148852, 2016).
colon carcinoma (12 papers, 2012 to 2022). "For example, the expression of ATP2B4, a Plasma membrane Ca2+ ATPases (PMCAs) known as the major ATP-consuming pumps responsible for Ca2+ extrusion from the cells, is repressed in colon cancer with mutated or WT KRAS or BRAF." (PMID 35267511, 2022). "Those that show significant changes are ATP2B4, which was downregulated in all the Furin-silenced colon cancer cells, and the P2Y receptor, which was specifically repressed in BRAF mutated colon cancer cells." (PMID 35267511, 2022). "These include the plasma membrane Ca2+ ATPase (ATP2B4), the purinergic receptor subtype P2RY2A and the calcium channel ORAI1, all upregulated in colon cancer and the calcium voltage-gated channels CACNA1H and CACNA1Cn were found to be downregulated in colon cancer." (PMID 35267511, 2022).
cardiac hypertrophy (8 papers, 2009 to 2021). "ATP2B4 (PMCA4b) is involved in calcium homeostasis and has a role in controlling cardiac hypertrophy in response to increased load on the heart." (PMID 19505295, 2009).
familial spastic paraplegia (7 papers, 2014 to 2025). "The plasma membrane Ca2+ exporter encoded by ATP2B4 has been found mutated in familial spastic paraplegia, and voltage-dependent calcium channels comprising the CACNA1E-encoded subunit α1E have been linked to synaptic plasticity, as has been SYT17." (PMID 40019676, 2025). "Interestingly, a missense mutation in ATP2B4, encoding PMCA4, is also associated with one form of familial spastic paraplegia and calcium dysregulation was proposed to be associated with the pathogenesis of this disease." (PMID 34948386, 2021).
cerebral malaria (6 papers, 2019 to 2026). A sequestration of Plasmodium falciparum in the brain, which can cause coma and/or seizures. "Although linked to protection in human studies, a murine model showed that PMCA4 (ATP2B4) does not affect parasite levels but contributes to experimental cerebral malaria." (PMID 41400477, 2026). "In contrast, ATP2B4 gene targeting in mice infected by Plasmodium berghei strain ANKA did not alter parasitaemia, although it protected against cerebral malaria." (PMID 36849945, 2023).
falciparum malaria (4 papers, 2019 to 2025). "Several SNPs within the ATP2B4 gene (human chromosome 1q32) linked PMCA4 with resistance to severe forms of falciparum malaria in numerous patients from Africa, Asia and Oceania." (PMID 41199322, 2025). "On study completion, all participants were genotyped both for Dantu and for four other polymorphisms that are associated with protection against severe falciparum malaria: α+-thalassaemia, blood group O, G6PD deficiency, and the rs4951074 allele in the red cell calcium transporter ATP2B4." (PMID 37310872, 2023).
pancreatic cancer (4 papers, 2016 to 2026). "Here, using the high-throughput metabolic CRISPR library screening and RNA sequencing, we identified an ATPase Plasma Membrane Ca2+ Transporting 4 (ATP2B4) as a novel molecular contributor to radiotherapy resistance in pancreatic cancer both in vitro and in vivo." (PMID 42185253, 2026).
Stroke (3 papers, 2018 to 2020). Sudden impairment of blood flow to a part of the brain due to occlusion or rupture of an artery to the brain. "One gene, ATP2B4, was associated with both “stroke” and “long survivor” groups." (PMID 32898326, 2020). "We have screened autoantibody levels in the sera of patients with ischemic stroke and report TUBB2C, ATP2B4, BMP-1, DHPS, and SH3BP5 as possible antigens that may be implicated in the development of stroke." (PMID 29507658, 2018).
atherosclerosis (2 papers, 2018). A disease characterized by the build-up of fatty material and calcium deposition in the arterial wall resulting in partial or complete occlusion of the arterial lumen. "For example, autoantibodies, such as those against RPA2, ATP2B4, and TUBB2C have been identified as atherosclerosis and/or CI markers." (PMID 29464021, 2018).
breast tumor (2 papers, 2012 to 2018). "Genes associated with the cardiotoxicity of doxorubicin (through negative effects on mitochondrial function when converted to doxorubicinol) also have altered expression in breast tumour cells upon selection for doxorubicin resistance, including ACO1, ATPS, CYCS, and ATP2B4." (PMID 22938713, 2012).
chronic kidney disease (2 papers, 2015 to 2016). Impairment of the renal function secondary to chronic kidney damage persisting for three or more months. "ATP2B4 and BMP-1 antibodies increase in atherosclerosis-related diseases, such as CI, CAD, DM and chronic kidney disease." (PMID 28936256, 2016). "We have recently reported novel atherosclerosis-related antibody markers, such as antibodies against RPA2 for stroke, antibodies against SOSTDC1 and TUBB2C for CI and DM, and antibodies against ATP2B4 and BMP-1 for atherosclerosis-related diseases, such as CI, CAD, DM and chronic kidney disease." (PMID 28936256, 2016).
COVID-19 (2 papers, 2024 to 2025). A disease caused by infection with severe acute respiratory syndrome coronavirus 2. "Of interest, we observed decreased levels of ATP2B1 and ATP2B4 in the lungs of COVID-19 patients, while the levels of ATP2A2 were found to increase (Fig. EV1G)." (PMID 38816514, 2024).
hypertrophic cardiomyopathy (2 papers, 2016 to 2022). A condition in which the myocardium is hypertrophied without an obvious cause. "Next, our KEGG analysis showed that transcripts up-regulated in the mutant cardiomyocytes were related to hypertrophic cardiomyopathy (ACTC1, MYL2, MYL3), Ca2+-dynamics regulatory pathway (ATP2B4, CACNA1C, CAMK2B, PLN), as well as cardiac-muscle contraction transcripts (ACTC1, MYH7, TNNI3, TNNT2)." (PMID 35784482, 2022).
lung carcinoma (2 papers, 2006 to 2021). "In keeping with the fact that lung cancer cells have more complex genetic landscapes than SCCOHT15,62, only four genes, namely ITPR3, MATN2, EHD4, and ATP2B4, were consistently upregulated by SMARCA4 in both cancer types." (PMID 34518526, 2021).
α-thalassaemia (2 papers, 2023). "We show that deletion of basigin ablates invasion while deletion of ATP2B4 has a minor effect and that erythroid cells from reprogrammed patient-derived HbBart α-thalassemia samples poorly support infection." (PMID 38173794, 2023). "We therefore typed individuals for α-thalassaemia, blood group O, G6PD deficiency and ATP2B4 alleles, and carried out the same set of analysis as above for each genotype." (PMID 37310872, 2023).
cardiomyopathy (1 paper, 2024). A disease of the heart muscle or myocardium proper. "The downregulation of two of the key cardiomyopathy stress genes, Myh6 and Atp2b4 (PMCA), in Het mice treated with HFD was confirmed at the protein level (Fig. EV3A–D)." (PMID 38724625, 2024).
colitis (1 paper, 2022). Inflammation of the colon. "Western blot analysis of the colon samples confirmed a reduction in plasm membrane Ca2+ pump proteins (PMCA), encoded by Atp2b1, Atp2b2, Atp2b3, and Atp2b4 and recognized by the same antibody, in colitis mice, which was rescued by BBR." (PMID 36528592, 2022).
Hip dysplasia (1 paper, 2017). The presence of developmental dysplasia of the hip. "Only 2 genes (HSPG2 and ATP2B4) were found to be linked to hip dysplasia or other skeletal or bone/joint abnormalities." (PMID 28327142, 2017).
invasive breast carcinoma (1 paper, 2018). A carcinoma that infiltrates the breast parenchyma. "We found that the expression of the ATP2B4 gene was downregulated in invasive breast carcinoma or invasive ductal breast carcinoma samples compared to normal breast tissues." (PMID 30352569, 2018).
mesothelioma (1 paper, 2015). A usually malignant and aggressive neoplasm of the mesothelium which is often associated with exposure to asbestos. "As result, the silencing of ATP2B4 promoted reactivation of the apoptotic machinery and sensitized mesothelioma cells to apoptotic stimuli." (PMID 26156019, 2015).
myeloma (1 paper, 2022). "Hence, myeloma-derived exosomal miR-4261 can be delivered to RBCs, and miR-4261 can downregulate the expression of ATP2B4 in target cells, leading to a reduction in PMCA4 protein expression." (PMID 36091107, 2022). "By screening RBC miRNA expression data and comparing these data with data in the miRDB and TargetScanHuman_7.2 databases, 30 miRNAs met the following three conditions simultaneously: expression in myeloma cells; lack of expression in normal RBCs; and target gene of ATP2B4." (PMID 36091107, 2022).
nasal polyps (1 paper, 2018). "GUSB and ATPase plasma membrane Ca2+ transporting 4 (ATP2B4) were identified as reliable genes for normalization of cystic fibrosis transmembrane conductance regulator (CFTR) gene expression in the nasal mucosa and nasal polyps in patients with cystic fibrosis." (PMID 29371606, 2018).
preeclampsia (1 paper, 2015). Preeclampsia is a hypertensive disorder of pregnancy that is characterized by new-onset hypertension with proteinuria presenting after 20 weeks of gestation, and depending on mild or severe forms may initially present with severe headache, visual disturbances, and hyperreflexia. "The expression of plasma membrane calcium-transporting ATPase 4 (ATP2B4) was associated with preeclampsia, however the relationships reported were not consistent between studies." (PMID 26510177, 2015).
pregnancy disorder (1 paper, 2024). A disorder that is related to pregnancy. "Moreover, in relation to pregnancy disorders, ATP2B4 had decreased mRNA and protein levels in syncytiotrophoblasts cultured from preeclamptic placental tissue, whereas PPP3R1 mRNA levels were increased in PE-associated placentas." (PMID 38455065, 2024).
Ventricular arrhythmia (1 paper, 2015). "ATP2B4 encodes a plasma membrane calcium ATPase that mediates neuronal nitric oxide signaling in cardiac myocytes and directly interacts with a gene, SNTA1, that has been implicated in hereditary ventricular arrhythmia and sudden, presumed arrhythmic infant death." (PMID 26448358, 2015).